PPARG (peroxisome proliferator activated receptor gamma)
Diseases named in the same sentence as PPARG in open-access papers (continued):
Sharing a sentence is not in itself a finding about the gene and the disease.
type 2 diabetes (741 papers, 2004 to 2026). "Inactivating mutations of PPARγ cause lipodystrophy and increased risk of type 2 diabetes (T2D) in humans." (PMID 40499650, 2025). "Originally recognized for its role in regulating lipid and glucose metabolism in diseases such as type 2 diabetes and dyslipidemia, PPARγ has now been implicated in modulating immune responses." (PMID 39911401, 2025). "Studies show that the drug class thiazolidinediones, used in type 2 diabetes treatment, inhibit dopaminergic neuron loss by peroxisome proliferator-activated receptor gamma (PPAR-γ) activation and act in a neuroprotective manner in PD animal models." (PMID 40429904, 2025). "Meanwhile, long-term usage of thiazolidinediones, the synthetic agonists of PPARγ used to treat type 2 diabetics, is associated with elevated risk of BC development." (PMID 39695138, 2024). "CPA serves as a second messenger and physiological inhibitor of PPARG, participating in the regulation of adipogenesis, glucose homeostasis, and processes associated with type 2 diabetes." (PMID 39590877, 2024). "The PPARG gene plays a crucial role in metabolic regulation and has been extensively studied for its association with type 2 diabetes and obesity." (PMID 39767130, 2024). "Another study found that a higher risk of type 2 diabetes is associated with the hypermethylation of the PPARG promoter in the pancreatic islets of diabetic patients, which negatively correlated with insulin secretion." (PMID 39595621, 2024). "Co-localisation analysis suggested that type 2 diabetes associations in the PPARG locus had a 92% and 84% probability of sharing a causal variant with ALT and AST, respectively." (PMID 37171501, 2023). "Polymorphisms of TCF7L2, IGF2BP2, CDKAL1, KCNQ1, and PPARG genes showed a strong contribution to type 2 diabetes." (PMID 36902173, 2023). "Our previous studies mainly focused on the PPARγ agonist pioglitazone, which was used in type 2 diabetes, to protect against RIRI and the underlying molecular mechanisms." (PMID 36082081, 2022). "IRS1 gene polymorphisms Gly972Arg and PPARγ Pro12Ala are 2 types of polymorphisms associated with predisposing to type 2 diabetes but having opposite effects in their effect on adiponectin levels." (PMID 36292779, 2022). "The fourth novel SNP, rs4135247, is shared by FIadjBMI and PCOS and is located near PPARG, a gene involved in the insulin signalling pathway in type 2 diabetes that has been found to be associated with PCOS susceptibility." (PMID 35771237, 2022). "Previous studies indicated a significant role of PPARG and PPARG gene polymorphisms in the pathogenesis of type 2 diabetes." (PMID 35207731, 2022). "Another approach for the same problem is using PPARα/δ dual agonists, such as GFT505, which have been shown to treat type 2 diabetes while altogether avoiding the cardiovascular risk of PPARγ agonists." (PMID 35003101, 2021). "The selective PPARγ agonist rosiglitazone is widely used to treat type 2 diabetes; however, this treatment is associated with an increased risk of MI and CV death." (PMID 34360540, 2021). "One of the actions that these thiazolidinedione PPARγ agonists have is to decrease inflammatory genes to prevent atherosclerotic complications associated with type 2 diabetes." (PMID 33776749, 2020). "For example, type 2 diabetes risk alleles in PPARG are associated with elevated risk of pancreatic cancer and reduced risk of colorectal cancer." (PMID 32705315, 2020). "Type 2 diabetes risk alleles in PPARG (encoding peroxisome proliferator-activated receptor γ [PPARγ]) and HNF1B (encoding hepatocyte nuclear factor 1 homeobox B) lower the risk of prostate cancer." (PMID 32705315, 2020). "PPARG Ala12 allele has been related to increased long-term weight gain, and also with a reduction in type 2 diabetes risk." (PMID 33250050, 2020).
type 2 diabetes (continued). "We suggest that this ability of TDQ to provide multifaceted actions in the IR of type 2 diabetes can be attributed to its biological actions associated with PPARγ activation and DGAT2 inhibition." (PMID 31019978, 2019). "In line with a major role in the regulation of vascular tone and blood pressure, mutations in PPARγ induce severe hypertension and type 2 diabetes." (PMID 30012954, 2018). "PPARG, a key gene in adipogenesis and a Type 2 Diabetes drug target was implicated by our study in adipose tissue response to fasting, replicating previous results in model organisms." (PMID 30193568, 2018). "Rosiglitazone and pioglitazone have previously been prescribed to treat type 2 diabetes, but their use has been hampered by harmful side effects associated with supraphysiological activation of PPARγ target genes." (PMID 30906767, 2018). "Among the synthetic ligands of PPARγ, thiazolidinediones, which are used to treat diabetes mellitus type 2, increase the risk of bladder cancer." (PMID 29565812, 2018). "In clinic, PPARγ Pro12Ala polymorphism is identified as one of the common risk polymorphisms for Type 2 diabetes in multiple GWAS studies." (PMID 30186237, 2018). "In 2003, a community-based, cross-sectional observational study to explore the relationship between the PPARG Pro12Ala polymorphism and blood pressure in male subjects with type 2 diabetes was performed in Swedish subjects." (PMID 28727849, 2017). "Phosphorylation of PPARγ is inhibited by Rosiglitazone which is linked to the efficacy of the drug in treating type 2 diabetes." (PMID 28656106, 2017). "Previous studies have shown an association of the PPARG Pro12Ala polymorphism with improved insulin sensitivity and reduced risk of type 2 diabetes, but, in contrast, higher BMI." (PMID 29303622, 2017). "Within a few years after obtaining market approval in 1996, the gene encoding PPARγ (PPARG) was found to contain a missense variant (Pro12Ala) that associates with type 2 diabetes susceptibility." (PMID 28447115, 2017). "Previous studies showed that PPARG plays an important role in adipose differentiation and in susceptibility to type 2 diabetes." (PMID 28727849, 2017). "A meta-analysis of 8 case-control studies and 2 family-based studies found that the PPARG A12 allele was associated with a reduced risk of type 2 diabetes." (PMID 26949382, 2016). "Six out of twenty selected genes with largest expression difference (CYP1B1, GPT), genes linked to PCOS (RAB5B) or type 2 diabetes (PPARG, SVEP1), and methylation (DMAP1) were replicated in a separate case-control study." (PMID 26975253, 2016). "For example, PPARγ activation results in anti-inflammatory and anabolic actions; hence, PPARγ agonists like rosiglitazone have been used in the management of type II diabetes, a disease caused by widespread resistance to insulin actions." (PMID 25714093, 2015). "In parallel with the important biological roles of PPARα, PPARγ has also been recognized as a therapeutic target to treat hyperglycemia associated with metabolic syndrome and type 2 diabetes." (PMID 26225954, 2015). "The gene-gene interaction between IRS1 Gly972Arg and PPARG Pro12Ala is of interest because the two polymorphisms exert opposite effects on type 2 diabetes predispositions." (PMID 24447396, 2014). "Until recently, the Pro12Ala polymorphism in the peroxisome proliferator-activated receptor gamma (PPARG) was one of the other few polymorphisms that demonstrated an alteration in type 2 diabetes susceptibility across different populations." (PMID 25309595, 2014). "Agonists of the nuclear receptor PPARγ are therapeutically used to combat hyperglycaemia associated with the metabolic syndrome and type 2 diabetes." (PMID 25083916, 2014). "We looked also into nuclear receptors and more specifically PPARγ, a target also associated to metabolic syndrome, inflammation and type-2 diabetes." (PMID 24695519, 2014).
type 2 diabetes (continued). "Simultaneous activation of PPARα, PPARδ and PPARγ by a single compound is being pursued to treat the multiple defects associated with insulin resistance, type 2 diabetes and the metabolic syndrome." (PMID 25143786, 2014). "A variant in PPARG (rs1801282, P12A) was found to be associated with type 2 diabetes, which is a risk factor for CAD." (PMID 25485937, 2014). "Dominant negative mutations in PPARγ are the cause of a monogenic disease characterized by severe insulin resistance, type 2 diabetes, and hypertension." (PMID 23431284, 2013). "The downregulation of mPGES-1/PGE2/EP4 pathway possibly contributes to the protective effect of PPARγ on type-2 diabetes-associated DN." (PMID 24489534, 2013). "The Pro12Ala polymorphism in PPARγ represents the first genetic variant with a broad impact on the risk and complications of type 2 diabetes." (PMID 23145084, 2012). "PPARγ polymorphism (Pro12Ala) has been found to be associated with various diseases including type II diabetes, cardiovascular disease, and several types of cancer." (PMID 22936949, 2012). "Many genetic variants have been associated with type 2 diabetes, but from a long list of candidate genes only three have unambiguously been associated with the disease: PPARG, KCNJ11 and TCF7L2." (PMID 20161779, 2010). "The most studied PPAR polymorphism, PPARG Pro12Ala,has been shown to be associated with reduced PPARG activity, and initial studies reporteda lower risk of type 2 diabetes associated with the Ala12 allele." (PMID 18288282, 2008). "Here the authors review the currentstatus of PPARγ research, with an emphasis on its role inthe causes and treatment of type 2 diabetes." (PMID 15203881, 2004). "By weighting the sample using inverse probability weights derived from probabilities of enrollment, we replicate 54% more known genome-wide association study (GWAS) variants than models not accounting for bias (e.g., associations between variants in PPARG and type 2 diabetes)." (PMID 41812654, 2026). "As PPARG upregulation is involved in type 2 diabetes susceptibility, it is possible that by reducing inflammation, the GFD might also influence this pathway." (PMID 39796519, 2024). "Co-localisation using marginal and conditional associations for type 2 diabetes and ER+ breast cancer in the PPARG locus reported a low posterior probability (H4<5%; posterior probability of distinct causal variants: ≤23%) of both traits sharing one or more causal variants within this region." (PMID 37171501, 2023). "Among them, rs1801282 is a confirmed type 2 diabetes susceptibility locus of PPARG." (PMID 31915541, 2019). "However, it is believed that dysregulation of peroxisome proliferator-activated receptors gamma (PPARγ) is linked to the development of metabolic conditions including type 2 diabetes." (PMID 29789516, 2018). "Similar result was reported that thiazolidinedione (TZD), targeting PPARγ, exerted the inhibitory effects on both osteoclastogenesis and osteoblastogenesis, and finally induced bone loss and increased higher risk of fracture in patients with type 2 diabetes." (PMID 29228681, 2017). "Some rare missense mutations in PPARγ may cause profound phenotypic changes in affected individuals, contributing to the risk of dyslipidemia, type 2 diabetes, and colon cancer." (PMID 28208577, 2017). "Studies have shown that PPARG polymorphisms might be associated with coronary artery disease, type 2 diabetes and metabolic syndrome." (PMID 28727849, 2017). "The genome wide association studies have identified various susceptibility genes, including several type 2 diabetes mellitus (T2DM) such as PPARG, TCF7L2, FTO, CDKN2A/2B, and IRS1 etc. to be associated with the risk of T2DM, though their definite relation with GDM remains to be explored further." (PMID 28083030, 2016).
type 2 diabetes (continued). "Similarly, the AJ cohort has a reduced frequency of the Ala12 variant (G allele at rs1801282) in the PPARG gene; the Ala12 variant, while rare in all populations, reduces risk for type 2 diabetes by a factor of 0.86." (PMID 22277159, 2012). "The variant in PPARG is a confirmed type 2 diabetes polymorphism at genome-wide significance level, while the rest are either novel putative type 2 diabetes susceptibility loci or variants in genes previously associated with diabetes risk at a conventional significance level." (PMID 21283750, 2011). "In the present report, we aimed at replicating the top nine novel associations with type 2 diabetes in seven loci in a Danish case-control study (excluding the previously investigated PPARG variant) followed by a meta-analysis of our data and reported association studies." (PMID 21283750, 2011). "Likewise, the Pro12Ala polymorphism within the exon 2 of PPARγ has beenalready linked to type 2 diabetes, insulin sensitivity, obesity, and cardiovasculardiseases." (PMID 18645613, 2008). "Consistently, finding suggests that the Pro12Ala polymorphism (rs1801282) within PPARG gene can be associated to diabetic nephropathy, with Pro allele leading to increased levels of albuminuria and more elevated serum creatinine values in adults with type 2 diabetes." (PMID 37338602, 2023). "Interestingly, recent studies of human PPARG revealed allele-specific expression in adipose tissue and led to the identification of a regulatory variant rs4684847 that is associated with risk of type 2 diabetes." (PMID 30497374, 2018). "In both colon cancer and type 2 diabetes, metabolic changes induced by upregulation of the Wnt/beta-catenin signaling and downregulation of peroxisome proliferator-activated receptor gamma (PPAR gamma) may help account for the frequent association of these two diseases." (PMID 28298922, 2017). "Among the three isoforms of PPARs (PPARα, PPARβ/δ, and PPARγ), PPARα plays an important role in the regulation of fatty acid oxidation and lipid metabolism and is beneficial for its protection against metabolic disorders associated with type 2 diabetes and obesity." (PMID 26225954, 2015). "In the case of PPARG rs1801282, the risk allele is responsible for increased fat storage and may have been advantageous in ancient environments with unpredictable food supply and high level of activity, but now predisposes to type 2 diabetes." (PMID 25145545, 2014). "Among them, rs2920502 and linked SNPs like rs2920500 could be particularly interesting because PPARG has been associated with the development of type 2 diabetes, atherosclerosis, and cancer, and because PPAR-γ agonists (e.g., thiazolidinedione) have been used to treat type 2 diabetes." (PMID 25222615, 2014). "In similar generalised linear regression models the PPARG allele C (Pro12) increased 2 hour insulin levels in the overall cohort (p = 0.009) and in the non-diabetic group only (p = 0.0003) after stratification by type 2 diabetes status, with a significant statistical interaction (p = 0.017)." (PMID 24447396, 2014). "Despite extensive research on PPARγ agonists for various diseases, their only approved clinical use remains as thiazolidinediones for type 2 diabetes." (PMID 40286240, 2025). "The management of type II diabetes using Thiazolidinediones (TZDs), which are PPARG agonists, is controversial because of their known adverse effects, including increased body fat, bone loss, edema, liver dysfunction, and potential cardiovascular risks." (PMID 40564064, 2025). "Peroxisome proliferator-activated receptor gamma (PPARG) ligands are potent insulin sensitizers used in type 2 diabetes treatment." (PMID 40564064, 2025). "Clinically, PPARγ agonists Such as TZDs Like pioglitazone and rosiglitazone are used to treat type 2 diabetes, while PPARα agonists like fibrates target hyperlipidemia and cardiovascular risks." (PMID 40926269, 2025).
type 2 diabetes (continued). "The activation of PPARG is associated with the regulation of endocrine factors, which has led to the development of specific PPARG agonists for the treatment of type II diabetes." (PMID 40650064, 2025). "Clinical studies have demonstrated the therapeutic potential of PPARγ agonists in reducing albuminuria in patients with type 2 diabetes." (PMID 40556756, 2025). "TZDs are PPARγ agonists that have been used for treating type 2 diabetes, but they also inhibit MPC with low micromolar potencies (2.7 μM)." (PMID 40249800, 2025). "Based on the important function of PPARG, various reversible covalent regulators targeting PPARG have been developed, showing high efficacy and safety in treating type 2 diabetes and reversing liver steatosis." (PMID 40565585, 2025). "While brown adipocyte-derived EVs have shown cardioprotective effects, treatment with rosiglitazone, a peroxisome proliferator-activated receptor-gamma (PPARγ) activator used for type II diabetes, has revealed harmful effects." (PMID 40001534, 2025). "PPARG genetic variants are also associated with WHR, type 2 diabetes, and some hematological traits." (PMID 39747859, 2025). "Accordingly, in mouse models, genetic ablation, or pharmacological inhibition of FABP4 protects against atherosclerosis and type 2 diabetes by a mechanism involving PPARγ activation, which antagonizes NF-κB-dependent cytokine production." (PMID 37688656, 2024). "Small molecules MRL24 and SR1664 can block the phosphorylation of PPARγ at serine 273, selectively modulate the PPARγ transactivation to insulin‐sensitivity genes, and improve type 2 diabetes." (PMID 38988496, 2024). "Pioglitazone (Piog) is a medication commonly used in the management of type 2 diabetes, and it works by activating the expression of peroxisome proliferator-activated receptor gamma (PPARγ)." (PMID 38377027, 2024). "In contrast, thiazolidinediones (TZDs), the synthetic full agonists of PPARγ with robust insulin‐sensitizing functions, have been used as first‐line drugs in the clinical treatment of type 2 diabetes." (PMID 38988496, 2024). "Canonical Wnt/β-catenin is upregulated, while PPARγ is downregulated in cancers, type 2 diabetes, and neurodegenerative diseases." (PMID 39272080, 2024). "Thiazolidinediones (TZD), a class of synthetic agonists of peroxisome proliferator-activated receptor gamma (PPARγ), initially used as insulin sensitizers for the treatment of type 2 diabetes, have been shown to affect cellular metabolism." (PMID 38594745, 2024). "PPARγ has also been reported to mediate the impact of As on increasing the incidence of type 2 diabetes through the PPARγ-mTORC2 signaling pathway." (PMID 38753618, 2024). "In vivo studies have revealed that the PPARG promoter is hypermethylated in the adipose tissue of type 2 diabetic patients, both in visceral and subcutaneous adipose tissues." (PMID 39595621, 2024). "Despite remarkable drug development efforts for some NR1 members, the therapeutic relevance of this protein family is still limited to a few targets and indications, such as PPARγ agonists in type 2 diabetes and RAR agonists in cancer." (PMID 38890295, 2024). "Thiazolidinediones—PPARγ agonists, commonly used as insulin sensitizers for type 2 diabetes—have also been studied for their ability to promote thermogenic gene expression in both white and brown adipocytes." (PMID 39519099, 2024). "PPARγ agonists are commonly used in the treatment of type 2 diabetes to increase sensitivity to insulin." (PMID 38992135, 2024). "Thiazolidinediones (TZDs), such as rosiglitazone and pioglitazone, are Peroxisome proliferator-activated receptor gamma (PPARγ) agonists initially used to control blood glucose levels in type 2 diabetes but have shown complex effects in AMD." (PMID 39720591, 2024). "These adipogenic and lipogenic effects of Moringa extracts through the regulation of PPARγ activity suggests their potential efficacy in preventing or treating type 2 diabetes." (PMID 39458951, 2024).